UCP2 (uncoupling protein 2)
Diseases named in the same sentence as UCP2 in open-access papers (continued):
Sharing a sentence is not in itself a finding about the gene and the disease.
breast carcinoma (continued). "Among many genes, we confirmed that UCP2 was over-expressed in rho0 epithelial cells, breast cancer cell lines and primary breast tumors." (PMID 21935467, 2011). "A recent study demonstrated that UCP2 overexpression increases breast cancer cells’ stemness." (PMID 39201646, 2024). "Moreover, miR-214 increases breast cancer cell sensitivity by targeting UCP2 and inhibiting cell autophagy." (PMID 37744277, 2023). "In breast cancer, there is a significant relationship between UCP2 and tumor grade." (PMID 37744277, 2023). "Overexpression of miR-133a could decrease doxorubicin resistance in the MCF-7/Dox breast cancer cell line by decreasing the expression of mitochondrial uncoupling protein 2 (UCP-2)." (PMID 35012539, 2022). "The authors stated that UCP2 could be a therapeutic target in breast cancer patients treated with tamoxifen." (PMID 35628447, 2022). "In recent years, many studies have shown increased UCP2 protein expression in a large number of human tumors compared to adjacent normal tissues (e.g., head and neck, skin, pancreatic, prostate, colon, gallbladder, breast cancer, etc.)." (PMID 36499405, 2022). "As Basal-like breast cancers are more sensitive to immunotherapy, UCP2 may be a target for immunotherapy in Basal-like BCs." (PMID 35874806, 2022). "Taken together, our study identified UCP-2 as a novel therapeutic target for HER2 positive breast cancer and UCP-2 inhibitor may have great potential to enhance the response rate and efficacy of trastuzumab therapy." (PMID 34146128, 2021). "This study demonstrates that: (i) the Warburg effect is mediated by UCP2; (ii) this protein is overexpressed in breast cancer and many other cancers; (iii) it promotes tumorigenic properties in vitro and in vivo; and (iv) genipin suppresses the tumour-promoting function of UCP2." (PMID 33924958, 2021). "Furthermore, our earlier study provided direct evidences that UCP-2 played an essential role in the development of doxorubicin-resistance in MCF-7 breast cancer cells." (PMID 34146128, 2021). "Consistently, our data in human breast cancer cell line (MCF-7) approve the existence of an UCP2/3 dependence of mitochondrial Ca2+ uptake fueling the hypothesis that UCP2 might play an important role in the energy balance of certain cancer cells." (PMID 27642082, 2016). "Likewise, MiR-214 sensitizes breast cancer cells to both tamoxifen and fulvestrant treatment by targeting UCP2." (PMID 27289382, 2016). "UCP2 overexpression has been observed after oxidative stress induced by respiratory chain inhibitors and has been related to the development of breast cancer in an orthotopic model." (PMID 27289382, 2016). "Hence, the human breast cancer cell line MCF-7 was also found to exhibit UCP2-dependent mitochondrial Ca2+ uptake." (PMID 27642082, 2016). "The overexpression of UCP2 has been shown in various tumors, including breast cancer." (PMID 27551323, 2016). "Similarly, a decrease in cell viability and clonogenicity, in addition to an increase in ΔΨm, ROS production, apoptosis and autophagy, was induced in breast cancer cells after both UCP2 inhibition by siRNA and cytotoxic treatments by tamoxifen." (PMID 27289382, 2016). "Based on the findings that exogenous expression of miR-133a in breast cancer cells attenuated its Doxorubicin resistance in vitro possibly by reducing the expression of UCP-2, we further explored the effect of overexpressing miR133a in tumor xenografts in vivo." (PMID 26107945, 2015). "To evidence this hypothesis, we analyzed the expression of miR-214 and UCP2 in human breast cancer tissue specimens." (PMID 26666173, 2015). "More interestingly, it was observed that the expression of UCP-2 was increased in MCF-7/Dox at both protein and mRNA levels, which indicates that miR133a/UCP-2 might be involved in the development of Doxorubicin resistance in breast cancer cell line MCF-7." (PMID 26107945, 2015).
breast carcinoma (continued). "To further elucidate the significance of miR-133a on the expression of UCP-2 in breast cancer, we found by luciferase assay that transduction of miR133a could reduce the transactivation of UCP-2 gene promoter in MCF-7/Dox cell line." (PMID 26107945, 2015). "In this study, UCP2 was found overexpressed in breast cancer tissue specimens." (PMID 26666173, 2015). "These in vivo findings coincided with what was found in vitro, provided direct evidences that the miR133a/UCP-2 axis might be a novel therapeutic target for conquering Doxorubicin resistance in current breast cancer treatment." (PMID 26107945, 2015). "We explored the role of UCP2 in affecting the 4-OHT-induced apoptosis in breast cancer cells." (PMID 26666173, 2015). "This suggests that miR133a might play an essential role in chemotherapy development by its direct regulation UCP-2 expression in breast cancer cells." (PMID 26107945, 2015). "As in vitro evidences indicated that miR133a and UCP-2 might be involved in Doxorubicin-resistance in breast cancer cells, their in vivo efficacy was further explored." (PMID 26107945, 2015). "Genipin was shown to inhibit breast cancer cell MDA-MB-231 migration and to change the invasive phenotype of breast cancer cells and UCP2 may be the possible target involved." (PMID 23029478, 2012). "Together, these studies suggest a tumor-promoting function of UCP2 in breast cancer." (PMID 21935467, 2011). "Therefore, in order to define the role of UCP2 in cancer, we over-expressed UCP2 in MCF7 breast cancer cells." (PMID 21935467, 2011). "We used a TARP5 slide to screen a breast carcinoma for UCP2 expression." (PMID 21935467, 2011). "A decrease in cell viability and clonogenicity were induced following inhibition of UCP2 expression by siRNA and application of tamoxifen in breast cancer cells, altogether suggesting that UCP2 expression and function might actively contribute to chemo-resistance in different types of tumors." (PMID 31159324, 2019). "Interestingly, decreased cell proliferation rate was observed in MCF-7/Dox transduced with UCP-2 shRNA compared to shScramble, which indicated that UCP-2 might mediate the Doxorubicin resistance in breast cancer cells." (PMID 26107945, 2015). "UCP-2 might be a novel therapeutically target for Doxorubicin-resistant breast cancer therapy." (PMID 26107945, 2015). "Interestingly, UCP2 over-expression has also been proposed to directly contribute to the Warburg phenotype and to development of tumors in an orthotopic model of breast cancer." (PMID 24027528, 2013). "In breast cancer, studies have demonstrated that SMAD4 promotes the ectopic expression of UCP2, triggering the glycolytic process and thereby promoting tumor growth." (PMID 38686046, 2024). "In the present study, we showed for the first time that trastuzumab treatment induced elevated expression of UCP-2, probably because of HER2 phosphorylation, using samples from HER2-positive breast cancer patient received trastuzumab neoadjuvant therapy." (PMID 34146128, 2021). "The parameters studied were: cell viability, hydrogen peroxide production, antioxidant enzymes and UCP2 protein expression, and lipid and protein oxidative damage in MCF-7 breast cancer cells." (PMID 32213883, 2020). "In this study, breast cancer cells with knockdown of UCP2 showed higher sensitivity to 4-OHT than negative control cells in induction of apoptosis, whereas overexpression of UCP2 attenuated the activity of 4-OHT." (PMID 26666173, 2015). "MiR-214 increased the sensitivity of breast cancer cells to TAM and FUL through inhibition of autophagy by targeting UCP2." (PMID 26666173, 2015). "The expression of miR-214 and uncoupling protein 2 (UCP2) was determined by RT-qPCR and Western blot in breast cancer cells and human breast cancer tissue specimens." (PMID 26666173, 2015). "MiR-214 increased the sensitivity of breast cancers to TAM and FUL through inhibition of autophagy by targeting UCP2." (PMID 26666173, 2015).
breast carcinoma (continued). "We confirmed the large increase in UCP2 expression and also found a significant increase in gene expression of UCP1 and 5 in the rho0 cells and breast cancer cell lines." (PMID 21935467, 2011). "In this study, we demonstrated a downregulation of UCP2 gene expression by (-)-epicatechin in MDA-MB-231 breast cancer cells, whereas in MCF-10A (noncancerous) cells, the opposite effect was observed." (PMID 40362341, 2025). "Further investigations revealed a negative correlation between miR-214 and UCP2 in human breast cancer tissues." (PMID 40190354, 2025). "In conclusion, UCP2 overexpression was detected in MDA-MB-231 breast cancer cells compared with MCF10A cells (noncancerous cells)." (PMID 40362341, 2025). "And this was accompanied by reduced expression of UCP-2 in tumor xenografts, indicating that the miR133a/UCP-2 axis could be a potential therapeutic target for breast cancer therapy." (PMID 26107945, 2015). "Levels of HER2 phosphorylation and UCP-2 expression were detected by immunohistochemistry (IHC) and compared between tumor needle biopsy tissue and surgical tumor samples of these patients, as well as in BT474 breast cancer cells before and after trastuzumab treatment." (PMID 34146128, 2021). "Here we report for the first time that UCP-2 overexpression was induced by HER2 phosphorylation in HER2-positive breast cancer, and this could be reversed by HER2 kinase inhibitor ONT-380, indicating potential signaling regulation of UCP-2 expression by HER2 phosphorylation." (PMID 34146128, 2021). "Importantly, a negative correlation was established between miR-214 and UCP2 in human breast cancer tissue specimens assayed by RT-qPCR." (PMID 26666173, 2015). "Considering the critical roles of UCP-2 in cancer progression and the potential correlation between HER2 signaling and UCP-2 expression, we proposed that suppression of UCP-2 might be a feasible way to increase initiate response rate and/or enhance efficacy in trastuzumab in breast cancer therapy." (PMID 34146128, 2021). "Moreover, we showed that UCP-2 inhibitor Genipin might enhance the tumor suppression effects of trastuzumab and induce apoptosis in BT474 cells, shedding some light on the development of novel combination therapy against trastuzumab resistance HER2 + breast cancer." (PMID 34146128, 2021). "In this study, two breast cell lines (MDA-MB-231 breast cancer cells and MFC10A noncancerous breast cells) were used to determine the possible regulation of UCP2 protein expression by (-)-epicatechin and its relationship with the resulting antiproliferative effect." (PMID 40362341, 2025).
Hyperglycemia (38 papers, 2008 to 2026). An increased concentration of glucose in the blood. "Diabetes-associated hyperglycemia seems to play a critical role in regulating the expression of UCP2." (PMID 36009191, 2022). "Taken together, the present study suggests that UCP2 deficiency enhances NLRP3 inflammasome activation by increasing ROS production in the context of hyperglycemia-exacerbated I/R damage." (PMID 33735403, 2021). "As expected, hyperglycemia caused more ischemic cell death than normoglycemic animals in both WT and UCP2-/- mice." (PMID 33061796, 2020). "In this study, we hypothesized that UCP2 deficiency enhances NLRP3 inflammasome activation after hyperglycemia-exacerbated cerebral I/R damage." (PMID 33735403, 2021). "Furthermore, UCP2 deficiency enhanced NLRP3 inflammasome activation after hyperglycemia-exacerbated cerebral I/R damage in vivo and in vitro." (PMID 33735403, 2021). "Furthermore, UCP2 deficiency enhanced NLRP3 inflammasome activation in neurons in the context of hyperglycemia-exacerbated cerebral I/R damage." (PMID 33735403, 2021). "Moreover, UCP2 deficiency enhanced NLRP3 inflammasome activation in neurons when cerebral I/R damage was exacerbated by hyperglycemia." (PMID 33735403, 2021). "Therefore, this study focused on the effect of UCP2 deficiency on the expression of inflammasomes in neurons in the context of hyperglycemia-exacerbated I/R damage." (PMID 33735403, 2021). "Therefore, this study focused on the effect of UCP2 deficiency on the expression of NLRP3 inflammasome components in neurons in the context of hyperglycemia-exacerbated cerebral I/R damage." (PMID 33735403, 2021). "Furthermore, UCP2 deficiency promoted NLRP3 inflammasome activation under hyperglycemia-exacerbated cerebral I/R damage." (PMID 33735403, 2021). "UCP2 deficiency aggravated hyperglycemia-induced exacerbation of cerebral I/R damage." (PMID 33735403, 2021). "Although the exact role of high and low UCP2 expression levels in these diseases is controversial, most studies indicate that increased UCP2 expression is generally associated with impaired insulin secretion and reduced β-cell function, contributing to hyperglycemia." (PMID 39707176, 2024). "The impaired mitochondria isolated from hyperglycemia-treated cells showed increased palmitoylcarnitine oxidation, decreased pyruvate oxidation, and Uncoupling protein 2 (UCP2)." (PMID 38645427, 2024). "Hyperglycemia enhances the detrimental effects of FFA since the respiratory chain uncoupling by UCP2 requires high membrane potential as reached at high glucose concentrations." (PMID 35453472, 2022). "In this study, we found that UCP2 deficiency exacerbated NLRP3 inflammasome activation and increased ROS production in neurons after hyperglycemia-exacerbated cerebral I/R damage in vivo and in vitro." (PMID 33735403, 2021). "UCP2 deficiency further increased the expression of NLRP3 and cleaved caspase 1 in neurons in the context of hyperglycemia-exacerbated cerebral I/R damage." (PMID 33735403, 2021). "In summary, our data suggest that UCP2 deficiency enhances NLRP3 inflammasome activation and ROS production after neurons in hyperglycemia-exacerbated cerebral I/R damage in vivo and in vitro." (PMID 33735403, 2021). "We evaluated the effects of UCP2 deficiency and the activation of the NLRP3 inflammasome in hyperglycemia-induced exacerbation of cerebral ischemic injury." (PMID 33735403, 2021). "Third, UCP2 deletion with hyperglycemia further expanded the infarct volume compared with WT mice under hyperglycemic condition." (PMID 33061796, 2020). "Reduction of UCP-2 expression in adult rat ventricular cardiomyocytes by hyperglycemia increases ROS formation and induces cardiomyocyte contractile dysfunction." (PMID 32120777, 2020). "In the present study, we demonstrated that hyperglycemia caused reduction of renal mitochondria SOD2 and enhancement of UCP2, then reduced ATP production by the mitochondria." (PMID 31406124, 2019).
Hyperglycemia (continued). "We can assume that UCP2 is highly upregulated during hyperglycemia in liver and its presence correlates with the adaptability of hepatic cells to high concentrations of extracellular glucose." (PMID 29949946, 2018). "Our results demonstrate that, under conditions mimicking the hyperglycemia, Complex I activity, UCP2, Complex III and IV subunits content, supercomplex formation, and acetylation levels are modified with respect to the control condition." (PMID 29949946, 2018). "Hyperglycemia-induced oxidative stress can inhibit the secretion of insulin in pancreatic beta cell through the activation of an uncoupling protein-2 (UCP-2) which lowers the ATP/ADP ratio by leaking protons in the β cell." (PMID 28497094, 2017). "In contrast, UCP2 overexpression improves both hyperglycemia- and high-salt diet-induced endothelial dysfunction and ameliorates hypertensive target organ damage in SHRSP." (PMID 29163755, 2017). "On the other hand, in the EA.hy926 venous endothelial cells, hyperglycemia by itself induced a ~1.5 fold increase in UCP2 expression and dexamethasone significantly reduced the expression of UCP2 both at the mRNA and at the protein level." (PMID 27128320, 2016). "Hyperglycemia-induced oxidative stress has been reported to inhibit the secretion of insulin in pancreatic beta cell through the activation of an uncoupling protein-2 (UCP-2) which lowers the ATP/ADP ratio by leaking protons in the β cell." (PMID 25821809, 2015). "In summary, we have demonstrated herein that administration of genipin attenuates hyperglycemia-induced podocyte lesion and therefore delays the progression of diabetic nephropathy through negatively regulation of UCP2 protein expression." (PMID 22848482, 2012). "Instead, a complex regulatory network centered on UCP2 likely exists, where high UCP2 levels may exert a protective effect in the pre-diabetic phase, but inhibit β-cell function under prolonged hyperglycemia." (PMID 39707176, 2024). "Under conditions of prolonged hyperglycemia, UCP2 expression in the liver can be downregulated." (PMID 39377070, 2024). "Thus, UCP2 acts as an essential sensor and negative regulator of mitochondrial ROS overproduction in response to hyperglycemia." (PMID 36009191, 2022). "UCP2 may be a potential therapeutic target for hyperglycemia-induced exacerbation of cerebral I/R damage." (PMID 33735403, 2021). "Genetic deletion of UCP-2 in mice enhances islet ATP generation and insulin secretion during glucose stimulation and reduces hyperglycemia in the ob/ob mice (a well-known diabetes type 2 mouse model), providing further support for the role of UCP-2 in the pathogenesis of the disease." (PMID 32528413, 2020). "Moreover, they are involved in oxidative stress pathway (probably by targeting UCP2), which is an important mechanism linking hyperglycemia to diabetic chronic complications." (PMID 31249597, 2019). "Thus, for example, glucocorticoids diminish mitochondrial superoxide formation by upregulation of UCP2 in endothelial cells upon hyperglycemia." (PMID 29351723, 2018). "They indicated that endothelial UCP2 may function as a sensor and negative regulator of mitochondrial ROS production in response to hyperglycemia." (PMID 29351723, 2018). "To test whether the glucocorticoid-mediated UCP2 induction also affects the metabolism in microvascular endothelial cells, we exposed the cells to hyperglycemia and followed the oxygen consumption and acid production in response to mifepristone." (PMID 27128320, 2016). "Thus hyperglycemia itself induces UCP2 expression in some cell types, eg. in beta cells and venous endothelial cells and we also observed increased expression level in the muscle in diabetic mice." (PMID 27128320, 2016). "UCP2 overexpression was able to inhibit the apoptosis of HUVECs induced by hyperglycemia." (PMID 26218518, 2015).